PPARG (peroxisome proliferator activated receptor gamma)
Diseases named in the same sentence as PPARG in open-access papers (continued):
Sharing a sentence is not in itself a finding about the gene and the disease.
infection (continued). "As inflammatory monocytes differentiate into dendritic cell subset, so-called tipDCs, within inflamed tissues, it is possible that PPARγ also controls the numbers of tipDCs at the site of infection." (PMID 22629382, 2012). "Increased PPARγ expression was apparent as early as 2 h after infection and reached maximal levels within 24 h after the infection." (PMID 22851964, 2012). "Based on the different targets of PPARγ in lipid metabolism, it is conceivable that PPARγ operates at different levels to regulate lipid droplet biogenesis during infection." (PMID 22851964, 2012). "Gene expression analysis of Listeria monocytogenes infected macrophages revealed regulation of PPARγ responsive gene sets indicating that PPARγ has likely undergone ligand-activation after infection." (PMID 22629382, 2012). "Here, we demonstrate that also the intracellular bacterium L. monocytogenes increases PPARγ expression rapidly within 30 minutes after infection of primary murine macrophages." (PMID 22629382, 2012). "Our computational simulation predicts an upregulation of miR-146b, and IL-17 and a down-regulation of NCOA4 and PPARγ in colons of mice after infection with C. difficile." (PMID 23071818, 2012). "By 15 min post-H37Rv infection, a decline of 17 cytokines combined with up-regulation of Ccl24 (26.5-fold), Clec4a2 (23.2-fold) and Pparγ (10.5-fold) indicated an anti-inflammatory response initiated by IL-13." (PMID 22039457, 2011). "Surprisingly, we found a 19.29-fold increase of PPARγ expression with Ad-rHNF4α infection relative to the Ad-GFP control." (PMID 22190905, 2011). "This study examined the impact of current and potential pharmacological targets namely the systemic corticosteroid dexamethasone and the peroxisome proliferator-activated receptor- gamma agonist pioglitazone on the outcome of infection in smoke-exposed mice." (PMID 20967263, 2010). "Ciglitazone at a concentration of 5 μMdecreased the T3-induced expression of Runx2 by 36%.Ad-PPARγ infection decreased the expression of Runx2 mRNAby 54% in the absence of ciglitazone and by 66% in thepresence of 5 μM of ciglitazone." (PMID 17259668, 2006). "Interestingly, we found enhanced expression PPARγ in the liver of the mice at 8 weeks post-infection." (PMID 41358489, 2025). "In addition, siRNA knockdowns of AT1 and PPARγ showed an insignificant change in infection upon TM treatment." (PMID 40810540, 2025). "This increased infection of PAMs led to an increase of granulocyte-monocyte colony-stimulating factor (GM-CSF) stimulation but a reduced expression of peroxisome proliferator-activated receptor gamma (PPARγ) in the sOH/04-infected group." (PMID 38377132, 2024). "Moreover, infection of Usp7-expressing adenovirus increased PPARγ levels in the liver of mice and accelerated the development of fatty liver." (PMID 36834633, 2023). "However, the heavy metal cadmium or infection mediated an inhibitory posttranslational modification of peroxisome proliferator-activated receptor γ (PPARγ) to exacerbate LRTIs." (PMID 36928191, 2023). "Therefore, the role of PPARγ in disease is complex and context-dependent, and more research is needed to fully understand the molecular mechanisms by which PPARγ regulates the host response to infection." (PMID 36831317, 2023). "We finally also investigated the effects of PPARγ KO on infection against S.T." (PMID 36519446, 2022). "The PPARγ agonist rosiglitazone stimulates an M2-like macrophage response, characterized by downregulation of iNOS, while dexamethasone treatment resulted in decreased immune cell migration to the infection site and reduced serum nitrate levels." (PMID 35575507, 2022). "In this respect, the pleiotropic role of PPARγ makes it an expected critical target of infection." (PMID 34445581, 2021). "However, activation of PPARγ enhances the resolution of extracellular bacteria-induced infection, such as P. aeruginosa and S. aureus." (PMID 33927725, 2021).
infection (continued). "This is further evidenced by how PPARγ responds to infection in vivo." (PMID 35003101, 2021). "In another independent study, infection with MERS-CoV upregulated PPARγ in human macrophages." (PMID 35003101, 2021). "In this respect, the pleiotropic role of PPARγ makes it a critical target of infection." (PMID 34445581, 2021). "Therefore, our data herein support the involvement of a macrophage PPARγ/CD36 pathway in host infection response." (PMID 33927725, 2021). "We found collectively among SP-A variants several genes such as AKT1, BTK, CCL9, PPARG, and RELA to exhibit higher expression in females, whereas, CFLAR, C1QC, LSP1, CKAP2, KAT2B, TACC2, and RCC2 exhibited higher expression in males after infection." (PMID 32670284, 2020). "In summary, our study shows that FABP5 promotes the resolution of CS and infection-induced inflammation and that it may do so through PPARγ activation." (PMID 30877402, 2019). "We further tested their contributions in the induction of ANGPTL4 by using their specific inhibitors and showed that the PPARβ/δ inhibitor GSK3787 as well as PPARγ inhibitor T0070907 could significantly attenuate the infection-induced upregulation of ANGPTL4." (PMID 31766605, 2019). "Host PPARG variants have also been found to provide resistance to infection by some, but not all, Hepatitis C virus strains." (PMID 31277567, 2019). "Alterations in IFNγ and PPARγ signaling may be a possible mechanism by which M1/M2 macrophage populations are altered in Stat2−/− mice in super-infection." (PMID 30337919, 2018). "Finally, using an in vitro macrophage infection model, we demonstrate that GM-CSF inhibition of M. tuberculosis growth requires the expression of peroxisome proliferator-activated receptor gamma (PPARγ)." (PMID 29066547, 2017). "To test this hypothesis, we transfected THP1 macrophages with siRNAs targeting IRAK-M and PPARγ prior to infection with the lentiviral particles." (PMID 28118607, 2017). "However, the results suggest that ECwt infection increases the percentage of villus cells being positive to both cytoplasmic and nuclear PPARγ in comparison to that of uninfected cells, whereas PGZ treatment appears to counteract this enhancing effect." (PMID 27382365, 2016). "Likewise, exposure of uninfected NSCs to 9-HODE recapitulated the effect of infection on PPARγ activity." (PMID 27078877, 2016). "However, the findings suggest that separately PGZ treatment and ECwt infection have a similar effect on PPARγ expression in cultured villi." (PMID 27382365, 2016). "However, PGZ treatment of uninfected villi led to an increased level of PPARγ expression that was similar to that induced by ECwt infection." (PMID 27382365, 2016). "The ECwt infection of PGZ-untreated villi led to further increased expression of PPARγ at 8 h.p.i." (PMID 27382365, 2016). "The reduction in PPARγ expression, which is more abundant in stellate cells, might be due to direct infection by HIV." (PMID 26735218, 2015). "Furthermore, we knocked down the expression of PPARγ at cellular level using shRNA interference via lentiviral infection of HK-2 cells." (PMID 23544048, 2013). "In summary, PPAR agonists and cPLA2 antagonist diminished 6k-PGF1α, PGF1α, and PGE1, and neither Leishmania infection nor LPS was able to recover their production; however, PGF2α production was increased after infection, and only PPARγ activation increased PGE2 production." (PMID 23555077, 2013). "Whether PPARγ+vs. PPARγ− cells within the Th1Th17 and also the Th1 pool are particularly permissive to infection and whether the nuclear localization of PPARγ contribute to limiting HIV permissiveness in such cells remains unknown." (PMID 24359430, 2013). "PPARγ prevents new infection by acting at levels prior HIV-DNA integration." (PMID 24359430, 2013).
infection (continued). "Our data indicates that EAEC-infected PPARγ deficient mice developed stronger inflammatory and effector responses towards EAEC early following the challenge ultimately leading to faster recovery from infection." (PMID 23469071, 2013). "Finally, PPARγ agonist increased the oxidative burst ~2.52-(P < 0.001) and ~3.55-fold (P < 0.001) at 60 and 120 min after infection, respectively; indicating that PPARγ activation induces an aggressive oxidative response to intracellular parasites." (PMID 23555077, 2013). "In addition, our laboratory has shown that in the developing lung PPARγ agonists can prevent lung injury induced by infection, nicotine, or hyperoxia." (PMID 22829803, 2012). "As the infection in the liver decreases, the expression of PPARγ subsides in coordination." (PMID 22448168, 2012). "As infection with L. monocytogenes leads to increased expression of PPARγ our results reveal a so far unrecognized regulatory network in myeloid cells that may be abused by L. monocytogenes to counter innate immunity." (PMID 22629382, 2012). "In addition to increased bactericidal activity, PPARγ ablation in myeloid cells resulted in enhanced recruitment of inflammatory monocytes to the site of infection." (PMID 22629382, 2012). "Of major interest during pathogen infection, PPARγ may repress target inflammatory genes, including proinflammatory cytokines and inducible NO synthase (iNOS)." (PMID 22851964, 2012). "Our results identify a so far unknown central role of PPARγ in the coordination of listeriocidal functions and recruitment of inflammatory monocytes to the site of infection." (PMID 22629382, 2012). "Indeed, myeloid-cell specific knockout of PPARγ rendered mice more resistant to infection with L. monocytogenes supporting the assumption that PPARγ expression can help bacteria to evade the early phases of innate immunity." (PMID 22629382, 2012). "Silencing of PPARγ in M. tuberculosis infected macrophages significantly enhanced iNOS expression and NO production in these cells while inhibited arginase I expression, suggesting an endogenous role for PPARγ in the downmodulation of NO production during infection." (PMID 22851964, 2012). "It has remained unclear whether PPARγ with its potent regulatory activity on innate immune functions in myeloid cells plays a regulatory role during infection with L. monocytogenes." (PMID 22629382, 2012). "Thus, our results demonstrate that PPARγ in myeloid cells has a central role in controlling both, the orchestration of bactericidal activity and immune cell recruitment to the site of infection." (PMID 22629382, 2012). "Because mature DCs capture and transfer HIV-1 to T cells with higher efficiency than immature DCs, we next determined whether PPARγ or LXR ligands could inhibit trans-infection mediated by LPS- or PAM3CSK4-matured MDDCs." (PMID 20617179, 2010). "Furthermore, we knocked down the expression of PPARγ using shRNA interference using lentiviral infection." (PMID 20650001, 2010). "By preventing DC migration in response to CCL21, PPARγ and LXR ligands may help to block the dissemination of DC-associated virus from mucosal sites of infection to regional lymph nodes." (PMID 20617179, 2010). "Infection of pigs with swine-adapted viruses depleted PAMs at 5 dpi most likely by triggering apoptosis in infected cells but it might also disrupt their immune activity and proliferation by repressing the expression of PPARγ." (PMID 38377132, 2024). "However, other researchers have hypothesized that PPARγ activation may impair the function of immune cells, such as macrophages, and contribute to the development of infections." (PMID 36831317, 2023). "Erythropoietin limits infections caused by Gram-negative Escherichia coli and Gram-positive S. aureus; macrophage-mediated clearance of these bacteria is at least partly mediated by a PPARγ-dependent pathway." (PMID 36831317, 2023).
infection (continued). "Notably, the activation of PPARγ in infection by HCMV is beneficial to viral replication." (PMID 34445581, 2021). "In summary, we postulate that targeting E2f1, Myc, Pparγ and Stat6 in M2-like macrophages induces a shift towards immunostimulatory M1-like macrophages, which may support immune defense and hence improve therapy against infection." (PMID 32097424, 2020). "In addition, cytomegalovirus promoter-mediated expression of PPARγ in white adipose tissue due to extrahepatic infection of adenovirus particles could increase the insulin-sensitizing effects of PPARγ and reduce indirectly hepatic lipid accumulation." (PMID 32411189, 2020). "Moreover, PPARγ activation induces the secretion of IL-8 that may contribute to demyelination as well as to the recruitment of immune cells to the site of infection and subsequent inflammation and tissue damage in infected nerves." (PMID 29979790, 2018). "Mice on a normal diet clear the infection within 14 days without regard to PPARγ deficiency." (PMID 27774097, 2016). "However infection or colonization trials on animal models using S. salivarius as a PPARγ inhibitor would be needed to prove this hypothesis." (PMID 25946041, 2015). "In addition, caprylic acid induces PPARγ mRNA expression in bovine mammary epithelial cells, which leads to the inhibition of NF-κB transcription factor that plays a key role in regulating the immune response to infection." (PMID 23509807, 2013). "As PPARγ is known to be up-regulated during infection of macrophages with Mycobacteria spp. or epithelial cells with Salmonella spp., we wondered whether infection of macrophages with Listeria monocytogenes would also increase PPARγ expression." (PMID 22629382, 2012). "As survival of L. monocytogenes in myeloid cells such as dendritic cells is critical for the successful establishment of infection, it appears likely that induction of PPARγ by L. monocytogenes is a critical step during infection and may serve as early escape from innate immunity." (PMID 22629382, 2012). "Given the importance of cholesterol for a number of aspects of HIV-1 biology, including virus binding and infection, we hypothesized that PPARγ and LXR signaling was altering the cholesterol content of DC membranes, thereby rendering them incapable of efficiently binding HIV-1 particles." (PMID 20617179, 2010). "Combined Pg infection and HFD produced the most severe phenotype, with synergistically elevated cytokines, heightened TLR4/NF-κB activation, marked suppression of PPARγ and Nrf2 signaling, reduced eNOS expression, and diminished nitric oxide bioavailability." (PMID 41750623, 2026). "While Mtb CDC1551 infection significantly upregulated the expression of IL8, expression of TLR4, PPARG, and STAT1 was significantly upregulated in Mtb HN878-infected trained and restimulated macrophages, compared to the cells without restimulation." (PMID 38980014, 2024). "A recent study showed that the inflammatory responses during infection with Chikungunya virus (CHIKV) involved the renin-angiotensin system (RAS) and PPARγ pathways." (PMID 36831317, 2023). "The released PPARG accelerates LDs degradation and AHL-12 prolongs the survival of host cells in infection via binding PLIN2." (PMID 34083514, 2021). "T. cruzi infection significantly decreased the expression of PPARγ in BAT and significantly increased PPARγ levels in WAT at 15 days after infection and this was probably due to their different responses to infection-induced inflammation." (PMID 31354939, 2019). "On the other hand, M2 macrophage-related genes (PPARγ, TGF-β, STAT3, IL5 and STAT6) were significantly up regulated after 24 h of infection." (PMID 30918280, 2019). "PPARα or PPARγ agonists reverted the infection-induced JNK and ERK phosphorylation while PPARα and PPARγ antagonist enhanced these phosphorylations." (PMID 29875768, 2018).
infection (continued). "To further confirm that IRAK-M, PPARγ and IL-10 were induced via the interaction of S glycoprotein with DPP4, we used siRNA approach to knock-down DPP4 in THP1 macrophages prior to infection." (PMID 28118607, 2017). "The concomitant effect of ECwt infection and PGZ treatment on the expression level of the cellular proteins PPARγ, PDI, and Hsc70 was examined." (PMID 27382365, 2016). "In characterizing the influence of ECwt infection on the expression of cellular proteins PPARγ, NF-κB, COX-2, PDI, and Hsc70, we found that these cellular proteins were certainly increased in their expression following ECwt infection." (PMID 27382365, 2016). "As expected, infection by native HCMV particles induced a dramatic and significant (p<0.01) increase in PPARγ activity in HIPEC." (PMID 26171612, 2015). "In view of the anti-inflammatory property and downregulation at site of infection in LNTB, further characterization of PPARγ in EPTB is warranted." (PMID 26469538, 2015). "Our data suggests a model whereby the pathogenesis of S. Typhimurium involves manipulation of the host innate immune and protease system, here illustrated by PPARγ, Lcn2 and MMP-9, to establish colonization and infection within the host." (PMID 24465207, 2014). "The expression of PPARG is reduced by intramammary infection with Escherichia coli and PPAR signaling was evidently inhibited by intramammary infection with Streptococcus uberis." (PMID 23737762, 2013). "Because of the limited number of samples, we were unable to conclusively show that expression of PPARγ and PON2 genes either changed or remained the same in individual patients upon infection with P. aeruginosa." (PMID 22860094, 2012). "PPARγ and LXR signaling repressed trans-infection of autologous primary T cells mediated by both immature, LPS-matured MDDCs, and PAM3CSK4-matured MDDCs, suggesting that the repression is independent of MDDC maturation." (PMID 20617179, 2010). "Most importantly, we found that PPARγ and LXR ligands inhibited trans-infection up to 5-fold underscoring their potential to limit HIV-1 transmission." (PMID 20617179, 2010). "Other TFs in the network (e.g., PPARG, TFAP2A, ZNF143) may modulate expression for homeostasis or fine-tune the response depending on infection stage." (PMID 41408150, 2025). "Considering that H37Ra infection was found to suppress the expression of PPARγ, it seemed that TLR2 signaling could downregulate the expression of PPARγ." (PMID 35432274, 2022). "We found that unopposed PPARγ activation suppresses bacterial clearance and blunts the induction of proinflammatory (but not anti-inflammatory, IL10) cytokines and ROS in response to infection both in vivo and in vitro." (PMID 35288651, 2022). "The results show that the infection with HAdV-D36 increased the expression of adipogenic genes C/EBPα, C/EBPβ and PPARγ, as well as intracellular lipid accumulation, regardless of the differentiation stage." (PMID 36237435, 2022). "Using immunofluorescence, we noticed that PPARG was redistributed from nuclei to cytoplasm and colocalized with PLIN2 after infection or AHL-12 treatment, and the redistribution could be weakened by silencing Tas2r138." (PMID 34083514, 2021). "By siRNA silencing of PPARG, we found that LDs did not further reduce after infection or AHL-12 treatments." (PMID 34083514, 2021). "Collectively, these results indicate that macrophage EPO signaling enhances noninflammatory E. coli clearance through PPARγ to promote infection resolution." (PMID 33927725, 2021). "Because PPARγ had been shown previously to be upregulated in human placenta cells infected by HCMV, NSCs from human embryonic stem cells were used as a model to investigate the outcomes on PPARγ activity of the infection of neural progenitors by HCMV." (PMID 34445581, 2021). "The levels of adiponectin were reduced (p<0.05), FABP4 levels were increased (p<0.01) and PPARγ levels were not changed during infection compared to the levels in control mice." (PMID 33826636, 2021).